APOE (apolipoprotein E)
Diseases named in the same sentence as APOE in open-access papers (continued):
Sharing a sentence is not in itself a finding about the gene and the disease.
vitamin D deficiency (11 papers, 2013 to 2025). A nutritional condition produced by a deficiency of VITAMIN D in the diet, insufficient production of vitamin D in the skin, inadequate absorption of vitamin D from the diet, or abnormal conversion of vitamin D to its bioactive metabolites. "This study highlights the independent role of vitamin D deficiency in modulating APOE genotypes in obese T2DM individuals." (PMID 39138505, 2024). "Multivariate logistic regression analysis was performed to evaluate 25 (OH) vitamin D deficiency as independent risk variables with the APOE genotyping (dependent variable) among obese cases and obese case with T2DM." (PMID 39138505, 2024). "We postulate that APOE ε4 regulates vitamin D transport, conferring resistance to vitamin D deficiency." (PMID 35149974, 2022). "This study examined the cardiovascular effects of dietary vitamin D deficiency and of vitamin D receptor agonist (paricalcitol) administration in apolipoprotein E knockout mice." (PMID 24586387, 2014). "Vitamin D deficiency increased mean arterial pressure by 14 mmHg relative to vitamin D-sufficient ApoE−/− mice (p<0.04)." (PMID 23349943, 2013). "Our findings highlight that APOE e4 genotype carries may benefit from improving handgrip and avoiding vitamin D deficiency." (PMID 37246226, 2023). "Notably, APOE ε4 is associated with a lower risk of vitamin D deficiency." (PMID 35149974, 2022). "Also, researchers stated that there is a clear and significant link between vitamin D deficiency and AD, even more than for APOE ε4; thus, maintaining 25-hydroxyvitamin D levels at 50 nmol/L or higher may be a viable approach to decrease the risk of AD and protect brain health." (PMID 39940989, 2025). "This study is designed to investigate the independent association between 25 (OH) vitamin D deficiency, HOMA-IR, and lipid profile with APOE genotyping in obese cases with and without T2DM." (PMID 39138505, 2024).
age (10 papers, 2014 to 2025). A temporal measurement of the time period elapsed since an identifiable point in the life cycle of an organism. "The ε4 allele of the apolipoprotein E gene (ApoE) is a well-established genetic vulnerability factor for pathologic and normal age-related cognitive decline." (PMID 35693343, 2022). "Therefore, it is critical to further evaluate the detrimental effects of the APOE ε4-allele on cognition in autistic males and females as they are more likely to develop age-related cognitive problems and early-onset Alz." (PMID 37958971, 2023). "Reduced cellular lipid exchange caused by deficits in ApoE function amplified cellular and inflammatory consequences of lipid stress, and emphasized ApoE as a therapeutic target in age-related neurodegeneration such as LBD and other dementia syndromes." (PMID 37947642, 2023).
AIDS (10 papers, 2011 to 2025). A syndrome resulting from the acquired deficiency of cellular immunity caused by the human immunodeficiency virus (HIV). "In HIV-positive patients, APOE E4 homozygosity is associated with a faster progression to AIDS and death and increases susceptibility to opportunistic infections." (PMID 40625502, 2025). "ApoE ε4/ε4 genotype was associated with an aggravated disease course of acquired immunodeficiency syndrome (AIDS), especially with accelerated progression to death." (PMID 21772670, 2011). "In fact, studies have shown that increased sialylation of ApoE correlates with elevated plasma ApoE and TG levels in humans with acquired immunodeficiency syndrome." (PMID 40180213, 2025). "APOE ɛ4 has been linked to AIDS severity and increased mortality especially in ɛ4 homozygotes." (PMID 34721516, 2021). "HIV/AIDS YDSK patients usually exhibited apathetic expression and decreased memory, which may be caused by the abnormal expression of ApoE." (PMID 29520099, 2018).
arteriolosclerosis (10 papers, 2017 to 2025). The thickening of the wall of the small arteries and arterioles. "APOE4, the major AD risk allele have also been reported to the severity of arteriolosclerosis in people with pathologic AD, whereas the ROS and MAP study has shown APOE ε2 has been associated with arteriolosclerosis severity but only among people over 90 years of age at death." (PMID 36324408, 2022). "The association between APOE ε4 and vascular neuropathologies aligns with some reports but contrasts with others, particularly those noting the role of APOE ε4 in macroinfarcts and arteriolosclerosis in specific populations—mostly community cohorts with smaller sample sizes." (PMID 40382659, 2025). "Odds ratios (OR) and 95% CIs for microinfarcts associated with arteriolosclerosis and CAA adjusted for possible modifying covariates such as age at death, sex, blood pressure, APOE genotype, Braak, and CERAD were estimated." (PMID 37298002, 2023). "The associations of TDP-43 pathology in amygdala and EC/inferior TCTX with arteriolosclerosis pathology were observed in the subjects with APOE −/− or −/ε4 genotype." (PMID 30567576, 2018). "By contrast, arteriolosclerosis pathology was associated with TDP-43 pathology in amygdala and EC/inferior TCTX when adjusted for sex, age at death, APOE genotype, and the type of TDP-43 antibody." (PMID 30567576, 2018). "We also observed that when adjusted for potential confounders, including age, sex, last systolic blood pressure, last diastolic blood pressure, APOE e4, Braak, and CERAD, the presence of moderate and severe arteriolosclerosis was associated with significantly higher odds of cerebral microinfarcts." (PMID 37298002, 2023). "To examine whether APOE genotype difference affects the association between TDP-43 pathology and arteriolosclerosis pathology, we further performed logistic regression analyses stratified by APOE genotype." (PMID 30567576, 2018). "Cardiovascular factors (systolic and diastolic blood pressure, heart rate, arteriolosclerosis), neuropsychological measures (Boston Naming, Mini‐Mental State Examination [MMSE]), and APOE genotype occupied the next tier of importance." (PMID 40791103, 2025).
bipolar disorder (10 papers, 2009 to 2025). A disorder of the brain that causes unusual shifts in mood, energy, activity levels and the ability to carry out day-to-day tasks. "This was also to some extent mirrored in an association study of APOE genotype and cognition in bipolar disorder, where the E2 allele presented improved cognitive performance while the presence of the E4 allele was associated with worse performance in some cognitive tasks." (PMID 38673634, 2024). "Based on predictions made through a bioinformatic study of miRNA with APOE as a regulatory target, miR-1908-5p was found to correlate with genes involved in bipolar disorder." (PMID 41301762, 2025).
bladder cancer (10 papers, 2012 to 2025). "The components of the 3-biomarker panel (VEGF, IL-8, APOE) have been associated with a number of cancers, including bladder cancer, to varying degrees." (PMID 23094052, 2012). "Similar to the poor prognosis in patients mediated by APOE, SERPINE1 and APOE are biomarkers of bladder cancer, both of which are highly expressed and mediate poor prognosis in patients." (PMID 37318594, 2023). "Univariate analysis indicated age, race, MMP9, IL8, VEGFA, CA9, PAI1, ApoE, A1AT, ANG and MMP10 were associated with bladder cancer." (PMID 33823873, 2021). "The expression of seven of the 10 bladder cancer -associated diagnostic signature (MMP9, MMP10, PAI1, CA9, APOE, SDC1, and ANG) showed a positive association with bladder cancer diagnosis, while IL8 and A1AT showed a negative correlation with cancer diagnosis." (PMID 31905599, 2019). "Relative to control cases, a reduction in SDC1 and overexpression of MMP9, MMP10, SERPINE1, IL8, APOE, SERPINA1, ANG were associated with high stage bladder cancer." (PMID 25387487, 2014).
Hyperinsulinemia (10 papers, 2010 to 2023). An increased concentration of insulin in the blood. "Thus, altered lipid and carbohydrate profile associated with hyperinsulinemia clearly highlights to ApoE-KO FD mice as a novel animal model with characteristics of human MetS." (PMID 33154969, 2020). "Among the mechanisms that may explain the higher prevalence of hyperuricemia in individuals carrying the ε4 allele of APOE polymorphism in our study could be the hyperinsulinemia associated with an unfavorable lipid profile." (PMID 21059196, 2010). "However, it remains unclear whether APOε4 allele modification is due to hyperinsulinemia, and hence deeper insight is needed to understand the pathogenesis of AD and how the APOE genotype can influence insulin metabolism." (PMID 37372995, 2023). "Moreover, HFD-induced hyperinsulinemia was also alleviated in ApoE-/- mice." (PMID 38062308, 2023).
periodontal disease (10 papers, 2009 to 2025). "The inoculation of Pg into the gingival pockets of the molars resulted in periodontal disease in ApoE-deficient mice, characterized by increased gingival pocket depths, local inflammation, alveolar bone loss, and systemic inflammation." (PMID 38892314, 2024). "Polymicrobial infection-induced periodontal disease is postulated to accelerate atherosclerotic plaque growth by enhancing atherosclerotic risk factors of orally infected Apolipoprotein E deficient (ApoEnull) mice." (PMID 23451182, 2013). "Thus, we induced periodontal disease using topical Pg inoculation into gingival pockets of ApoE-deficient mice to establish Pg DNA aggregates in the gingival pocket (Pg-induced periodontal disease) and to investigate the effect of GV1001 on the development and severity of periodontal disease." (PMID 38892314, 2024). "In this study, we aimed to investigate the effects of NIR-PBM on systemic oxidative stress and inflammation in an apolipoprotein E (ApoE) knockout mouse model of periodontal disease (PD)." (PMID 37817126, 2023). "In our study, apoE−/− mice with periodontal disease after 4 weeks of ligation established a disturbed gut microbiome." (PMID 33072621, 2020). "Directly neighboring this pair of genes is APOE, which is interestingly partnered with periodontal disease." (PMID 19208189, 2009).
progressive supranuclear palsy (10 papers, 2018 to 2025). A rare late-onset neurodegenerative disease characterized by supranuclear gaze palsy, postural instability, progressive rigidity, and mild dementia. "Another study has shown that the APOE ε2 allele is associated with a greater tau burden in brains with progressive supranuclear palsy (PSP) and that those with APOE ε2/ε2 genotype were found to have increased risk of PSP and corticobasal degeneration." (PMID 33287896, 2020). "We also show that in humans, the APOE ε2 allele is associated with increased tau pathology in the brains of progressive supranuclear palsy (PSP) cases." (PMID 30348994, 2018). "Moreover, the authors have found a significant association between the APOE ε2/ε2 genotype and increased risk of progressive supranuclear palsy." (PMID 33261653, 2020). "Here the authors show that mice expressing the human APOE ε2/ε2 genotype have increased tau pathology and related behavioral deficits; they also find that the APOE ε2 allele is associated with an increased burden of tau pathology in postmortem human brains with progressive supranuclear palsy." (PMID 30348994, 2018). "APOE polymorphisms affect the risk of progressive supranuclear palsy, which does not feature Aβ pathology, and APOE alleles modulate tau pathology independent of Aβ in animal models." (PMID 35508140, 2022).
prostate tumor (10 papers, 2013 to 2025). "Furthermore, APOE, secreted by prostate tumor cells, has been linked to cellular senescence and is associated with adverse prognoses." (PMID 39494300, 2024). "For example, APOE secreted by prostate tumor cells can bind to neutrophils via TREM2, inducing cell senescence." (PMID 40678806, 2025). "For instance, prostate tumor cells secrete APOE, which binds to TREM2 on neutrophils to promote their senescence." (PMID 39990672, 2025). "Recent studies have indicated that APOE secreted by prostate tumor cells binds to triggering receptor expressed on myeloid cells 2 (TREM2) on neutrophils, thereby promoting their senescence." (PMID 39524226, 2024). "Prostate tumor cells secrete increased amounts of APOE, which binds to TREM2 on neutrophils, inducing senescence." (PMID 38067270, 2023).
acute coronary syndrome (9 papers, 2007 to 2023). Signs and symptoms related to acute ischemia of the myocardium secondary to coronary artery disease. "P2Y12 receptor represents a further very promising molecule for the treatment of the disease as its inhibitor Ticagrelor reduces cardiovascular events in patients with acute coronary syndrome and decreases inflammatory endothelial activation and vascular dysfunction in ApoE-/- mice." (PMID 33664731, 2020). "In addition, excessive inflammatory deregulation also caused changes in HDL profile indicated by proteomics studies on the HDL from acute coronary syndromes (ACS) patients showed increases in apoA-IV and apoE, suggesting a critical role of HDL remodeling in acute diseases." (PMID 33148285, 2020).
Arthritis (9 papers, 2004 to 2024). Inflammation of a joint. "Although the presence of arthritis in ApoE−/− mice was associated with increased levels of G-CSF, KC/Gro-a and decreased levels of IL-21, IL-23 and MIP-2, the greatest change was observed in IL-6." (PMID 27287704, 2016). "The induction of arthritis was correlated with a 27-fold increase of serum IL-6 in arthritic ApoE−/− mice compared to arthritic C57BL/6 mice." (PMID 27287704, 2016). "Taken together, these results indicate that ApoE−/− mice demonstrate enhanced arthritis compared to C57BL/6 mice." (PMID 27287704, 2016). "Here, we examined the development of arthritis in ApoE−/− mice compared to controls using a semi-chronic K/BxN serum transfer-induced arthritis (STIA) model." (PMID 27287704, 2016). "Taken together, these studies demonstrate that ApoE itself has a major effect on the development of arthritis, which may be mediated through the formation of foamy macrophages within the synovium." (PMID 27287704, 2016). "However, using a modified chronic STIA model, more recent evidence demonstrated that ApoE-deficient mice display aggravated development of arthritis but not an increased plaque burden." (PMID 28724439, 2017). "K/BxN serum transfer-induced arthritis (STIA) was assessed in C57BL/6 (control) and ApoE−/− mice using clinical indices and immunohistochemical staining." (PMID 27287704, 2016). "We therefore injected into arthritic mice recombinant TGF-β with MMP2, ApoE, C1q, Ttr and Thbs1 but with no success, we did not observed arthritis resolution compared to SuperMApo injection." (PMID 30542342, 2018).
autoimmune disease (9 papers, 2010 to 2026). A disorder resulting from loss of function or tissue destruction of an organ or multiple organs, arising from humoral or cellular immune responses of the individual to their own tissue constituents. "The involvement of apoE in MS, although far from being elucidated, has been indicated by identification of the 19q13 chromosome as a candidate gene for autoimmune diseases from linkage analysis, such as systemic lupus erythematosus." (PMID 20613949, 2010). "Cytokines are crucial in human inflammatory and autoimmune disorders and apoE might affect these disorders through interacting with cytokines." (PMID 21772670, 2011). "However, the role of apoE in facilitating lipid antigen presentation by CD1 molecules to NKT cells has been extrapolated to be of great importance in autoimmune diseases." (PMID 20613949, 2010). "Anyway, the elucidation of the exact mechanisms by which apoE functions on the immune responses is appealing in that it may provide new insights to the preventive or therapeutic strategies in coping with autoimmune diseases and even other diseases." (PMID 20613949, 2010). "In terms of CD1-mediated self-lipid presentation, apoE might be involved in autoimmune diseases like MS via facilitation of self-lipid antigen presentation to NKT cells." (PMID 20613949, 2010).
Autoimmunity (9 papers, 2010 to 2025). The occurrence of an immune reaction against the organism's own cells or tissues. "Notably, ApoA-I deficiency did not exert converse effects on autoimmunity or glomerulonephritis, potentially attributable to compensatory elevations of ApoE within high-density lipoprotein (HDL)." (PMID 40260097, 2025). "In the ApoE−/- mouse AS model induced by the Western diet, anti-HMGB1 antibodies were more than six times higher than regular diet ApoE−/- mice and ApoE+/+ mice, indicating that HMGB1 autoimmunity is involved in the progression of AS." (PMID 35281098, 2022). "Aside from ApoE and C1q/C3, iron inhibits α-secretase or ADAM-10, the enzyme involved in the generation of soluble TREM-2 (sTREM-2), linking again this biometal to autoimmunity." (PMID 30564191, 2018).
diabetic neuropathy (9 papers, 2005 to 2025). A chronic, pathological complication associated with diabetes mellitus, where nerve damages are incurred due to diabetic microvascular injury involving small blood vessels that supply these nerves, resulting in peripheral and/or autonomic nerve dysfunction. "An association between the APOE genotype and disease outcome has been demonstrated for human patients with diabetic neuropathies, but very few have investigated the influence of the apoE isoform on the PNS in genetically modified animals." (PMID 32075060, 2020). "This review suggests that polymorphism within ACE, AKR1B1, APOE, MTHFR, NOS3, and VEGF may act as common genetic risk factors for the diabetic neuropathies in T2DM." (PMID 26074879, 2015).
diabetic retinopathy (9 papers, 2010 to 2025). "In type 2 diabetes patients with or without diabetic retinopathy, multivariate logistic regression analysis showed that APOC2/APOC3 and APOB/non‐HDL cholesterol, as well as APOE/APOC2, were independently related to the risk for the occurrence and severity of diabetic retinopathy." (PMID 37448184, 2023). "Although the lipid profile of the ApoE−/− differs somehow from that of dyslipidemic human subjects, we suggest that this model may be relevant for addressing the issue of inflammation and/or endothelial activation in diabetic retinopathy." (PMID 20856927, 2010). "In addition we found ALDH1A1, RBP4, APOB, APOA1, RBP1, APOE and RHO genes enriched in retinoid metabolic process as unique GO in diabetic retinopathy." (PMID 28761062, 2017).
Gliosis (9 papers, 2017 to 2025). Gliosis is the focal proliferation of glial cells in the central nervous system. "We then tested whether the R136S mutation protects against APOE4-driven gliosis in 10-month-old PS19 mice with different APOE genotypes." (PMID 37957317, 2023). "Despite gliosis is a feature of retinal pathology, our results showed absence of GFAP reactivity in MGCs in ApoE-KO FD mice retinas at 4 months." (PMID 33154969, 2020).